IDO1 (indoleamine 2,3-dioxygenase 1)
Diseases named in the same sentence as IDO1 in open-access papers (continued):
Sharing a sentence is not in itself a finding about the gene and the disease.
colorectal cancer (89 papers, 2006 to 2026). A primary or metastatic malignant neoplasm that affects the colon or rectum. "Our study demonstrates for the first time that the BRAF V600E mutation significantly elevates IDO1 expression in colorectal cancer." (PMID 39934467, 2025). "IDO1 is an enzyme catalysing the conversion of tryptophan to kynurenine and has been directly associated with tumourigenesis, as IDO1+ Paneth cells promote immune evasion in sporadic colorectal cancer." (PMID 39242821, 2024). "The expression of IDO1 in colorectal cancer as well as other malignancies is associated with poor prognosis." (PMID 36653774, 2023). "IDO1 expression was associated with an unfavorable clinical outcome in esophageal cancer and colorectal cancer." (PMID 36059952, 2022). "IDO1 is a catabolic enzyme involved in the pathways of tryptophan metabolism and plays a role in immune suppression The increased expression of IDO1 in ovarian, endometrial and colorectal cancers has been associated with poor survival outcomes." (PMID 29304754, 2018). "IDO-1 is highly expressed in human tumor cells and consequently creates an immunosuppressive microenvironment that has been associated with poor prognosis notably in colorectal cancer." (PMID 30619249, 2018). "Therefore, it remains to be seen whether IDO1 inhibition has a role in the treatment of inflammation-associated colorectal cancer, and this potential needs to be fully explored." (PMID 39242821, 2024). "Specifically, IDO1, a metabolic enzyme involved in tryptophan metabolism and an interferon-induced checkpoint molecule associated with immune suppression, has been linked to many types of cancer, such as acute myeloid leukaemia, ovarian cancer or colorectal cancer." (PMID 35379165, 2022). "In human colorectal cancer cells, IDO1 inhibition reduces nuclear activated β‐catenin levels, diminishes transcription of its target genes (e.g., cyclin D1 and Axin2), and hampers cell proliferation." (PMID 40103267, 2025). "This study constructed novel T cell dysfunction molecular subtypes for BRAF V600E-mutant colorectal cancer and identified IDO1 as a potential immunotherapy target, providing a new strategy for immunotherapy." (PMID 39934467, 2025). "For instance, USP14 is necessary to inhibit TRIM21-mediated K48 ubiquitination of IDO1, leading to increased IDO1 levels in colorectal cancer and promoting tumor cell immune evasion." (PMID 39990235, 2025). "Sun found that in colorectal cancer patients, changes in gut microbiota decreased fecal indole, raised Kyn and Kyn/Trp ratios, and the Kyn/Trp ratio was positively correlated with IDO1 expression in tissues." (PMID 40103267, 2025). "Increased expression of IDO1 in the intestinal epithelium of colorectal cancer patients promotes tumourigenesis and influences prognosis, likely through the activation of β-catenin by Kyn, a metabolite of the kynurenine pathway." (PMID 40040508, 2025). "In particular, in colorectal cancer models, IPA reverses the state of immune tolerance caused by aberrant IDO1 activity by restoring the tryptophan-indole metabolic axis, providing a theoretical basis for cancer immunotherapy targeting metabolic remodeling." (PMID 40825672, 2025). "Ultimately, using machine learning algorithms and bioinformatics validation, we identified IDO1 as a potential immunotherapy targets for BRAF V600E-mutant colorectal cancer." (PMID 39934467, 2025). "For instance, in colorectal cancer mouse models, miR-153 inhibits IDO1 expression in tumour cells, thereby enhancing the efficacy of CAR-T therapy (Ref." (PMID 40040508, 2025). "In the current study, we conducted in vitro and in vivo experiments to investigate the antitumor effects of combining an IDO1 inhibitor with radiation for colorectal cancer." (PMID 36653774, 2023). "1-L-MT (1-L-Methyltryptophan), a competitive inhibitor targeting IDO1, has the potential to suppress the proliferation of human colorectal cancer cells by inducing mitotic cell death." (PMID 37689664, 2023).
colorectal cancer (continued). "IDO1 expression has been detected in a variety of cancers, including colorectal cancer, along with high kynurenine and low indole content." (PMID 38169949, 2023). "Another study demonstrated that IDO1 inhibition sensitized colorectal cancer to radiation-induced cell death." (PMID 36983678, 2023). "In a clinical study, IDO1 was expressed in some patients with melanoma, lung, breast, esophagus, stomach, or colorectal cancers." (PMID 36653774, 2023). "To illuminate the biological significance of IDO1/COX2 in patients with liver oligometastases of colorectal cancer, we used immunohistochemical staining to test the expression of IDO1 and COX2 in 107 specimens." (PMID 36983678, 2023). "We investigated the antitumor effects of combination therapy of an IDO1 inhibitor, 1-methyl tryptophan (1-MT), and radiation on colorectal cancer." (PMID 36653774, 2023). "While investigating in detail the IDO1 role in colon cancer development, we found a report that suggests that the enzyme is directly involved in colorectal cancer (CRC) proliferation, and that its inhibition improves colon cancer management." (PMID 38201550, 2023). "For example, colon tissue from patients with inflammatory bowel disease and colorectal cancer is often accompanied by high expression of IDO1." (PMID 37468922, 2023). "The IDO1 inhibitor epacadostat is extensively employed in the clinical investigation of numerous types of tumors, including colorectal cancer." (PMID 37689664, 2023). "The effect of IDO1 inhibition on the proliferation of colorectal cancer cells was investigated using MTS assay." (PMID 36653774, 2023). "Activation of the cGAS-STING pathway increases IDO1 expression, which has been validated in colorectal cancer." (PMID 36353640, 2022). "Higher levels of IDO1 have also been detected in hypermutated colorectal cancers, suggesting a link with clinical benefit who receives anti-PD-1, anti-PD-L1, and anti-CTLA4 treatment." (PMID 35711437, 2022). "Here, we show a post-transcriptional regulatory mechanism of IDO1 regulated by a proteasome-associated deubiquitinating enzyme, USP14, in colorectal cancer (CRC)." (PMID 36163134, 2022). "It has been demonstrated that IDO1 inhibition can enhance the efficacy of radiotherapy in colorectal cancer." (PMID 35903691, 2022). "In some studies, IDO1 enzymatic activity can directly influence radiation sensitivity, such as colorectal cancer." (PMID 34504628, 2021). "IDO1 has also been shown to be expressed in colorectal cancer (CRC) cell lines, and its expression at the tumour invasion front is involved in CRC progression." (PMID 32776284, 2020). "In fact, IDO1 was described as an independent prognostic marker for increased disease-free survival in patients with colorectal cancer." (PMID 32486450, 2020). "In colorectal cancer, overexpression of IDO1 suppressed the CD8 T cell responses, leading to enhanced tumor growth." (PMID 32722019, 2020). "We expect that as solid tumor-specific CARs are developed, the combination of CAR T cells and IDO1 inhibition by miRNAs or other pharmacological approaches will be an effective treatment option for colorectal cancer and other solid tumors." (PMID 29685162, 2018). "We analyzed miR-153 expression in relationship to IDO1 mRNA levels in patients with colorectal cancer and found a significant inverse correlation between miR-153 and IDO1 mRNA levels (P = 0.04, R2 = 0.23)." (PMID 29685162, 2018). "For instance, IDO1-expressing colorectal cancer cells are more likely to metastasize to distant organs." (PMID 29156701, 2017). "Higher IDO1 expression was shown to be involved in colorectal cancer (CRC) progression and to be correlated with impaired clinical outcome." (PMID 27578919, 2016). "Indole synthesis is reduced while Kyn and IDO1 expression is up in colorectal cancer." (PMID 40825672, 2025). "Notably, we also identified IDO1 as a potentially immunotherapy target for patients with BRAF V600E-mutant colorectal cancer." (PMID 39934467, 2025).
colorectal cancer (continued). "Moreover, noncanonical regulatory mechanisms have attracted attention—for instance, the USP14 inhibitor IU1 has been reported to downregulate IDO1 expression and restore T cell–mediated antitumor responses in colorectal cancer models." (PMID 40666095, 2025). "Importantly, using machine learning algorithms, we identified IDO1 as a potential immunotherapy target in BRAF V600E-mutant colorectal cancer, offering a new strategy for treatment." (PMID 39934467, 2025). "The results of our current study reveal that CEA and IDO-1/COX2 may serve as feasible biomarkers for the prognostic prediction to predict CRC patients with liver oligometastases of colorectal cancer OS and PFS." (PMID 36983678, 2023). "In addition, USP14 stabilized indoleamine 2,3 dioxygenase 1 (IDO1) and enhanced immune suppression in colorectal cancer." (PMID 36733484, 2023). "We also performed multivariate Cox modeling to analyze whether traditional clinicopathological parameters and IDO-1/COX2 coexpression represent potential independent predictors for OS outcome in patients with liver oligometastases of colorectal cancer." (PMID 36983678, 2023). "Furthermore, IDO1 expression is correlated with poor prognosis in clinical outcomes in patients with colorectal cancer." (PMID 36545214, 2022). "The results indicated that IDO1 macrophages were closely related to colorectal cancer." (PMID 36248886, 2022). "Moreover, IDO1 macrophage subset was different from other macrophage subsets, which was the only macrophage subset presented almost exclusively in colorectal cancer tissue." (PMID 36248886, 2022). "IDO1 is overexpressed in many malignant tumors, but particularly in colorectal cancer." (PMID 36545214, 2022). "Whilst the positive correlation of activities between IDO1 and IFN-γ is strong in colorectal cancers, for example, it is relatively weak in ovarian or kidney cancers such that they may show great IDO1 expression but less activity of IFN-γ." (PMID 34539663, 2021). "In colorectal cancer l-kynurenine was not unequivocally associated with IDO-1 expression, suggesting that the mere expression of tryptophan catabolic enzymes is not sufficiently informative for optimal immunotherapy." (PMID 25881064, 2015). "At stage-III colorectal cancer patients, decisions for adjuvant treatment are weighed against possible side effects in patients with important comorbidity and the analysis of IDO1 expression at the tumour invasion front was suggested to be of additional value in the decision process." (PMID 26359356, 2015). "Here we examined a possible contribution of IDO1 on this phenomenon and investigated whether IDO1 has prognostic value in colorectal cancer (CRC)." (PMID 22108515, 2012). "Similarly, miR-153 has also been shown to target IDO1 in colorectal cancer in response to IFNγ." (PMID 32722019, 2020). "In colorectal cancer, Lactobacillus gallinarum‐derived ICA enhances anti‐PD‐1 therapy by regulating the IDO1/Kyn/AhR axis." (PMID 40103267, 2025). "In colorectal cancer (CRC), knocking down USP14 can inhibit IDO1 expression, enhance CD8+ T cell activity and numbers, and make CRC cells more sensitive to immunotherapy." (PMID 39315102, 2024). "Unsupervised clustering analysis divided colorectal cancer into three subtypes with distinct prognostic outcomes, and correlation analysis revealed the synergy among B cells, CD68+IDO1+TAMs, and T lineage cells in producing an effective immune response." (PMID 38951801, 2024). "To gain insights into the role of the IDO1/COX2 expression levels in CRC, we correlated IDO1/COX2 expression levels in 107 patients with liver oligometastases of colorectal cancer using 11 widely recognized clinicopathological features." (PMID 36983678, 2023). "In colorectal cancer (CRC), lnc-Sox5 induces indoleamine 2,3-dioxygenase 1 (IDO1) expression, which is known to promote Treg cell differentiation." (PMID 37346034, 2023).
colorectal cancer (continued). "A dual inhibitor targeting IDO1/TDO, HTI-1090, has been introduced into clinical trials for late-stage solid tumors, including colorectal cancer (NCT03208959)." (PMID 37689664, 2023). "In this study, we conducted a retrospective analysis of the potential prognostic importance of the correlation of IDO1/COX2 expression in OS and PFS in CRC patients with liver oligometastases of colorectal cancer." (PMID 36983678, 2023). "Here, the authors show that deubiquitinase USP14 regulates immune suppression by inducing IDO1 stabilization and suggest USP14 as a potential therapeutic target to improve immunotherapy in colorectal cancer." (PMID 36163134, 2022). "In support of this result, IDO1 expression in Paneth cells has been observed to be strictly regulated by STAT1 and regarded as an immunosurveillance escape strategy of colorectal cancer." (PMID 34946170, 2021). "Since IDO1-dependent KYN synthesis has been shown to directly promote colorectal cancer (CRC) growth through β-catenin activation, IDO inhibition has emerged as a promising strategy for CRC prevention." (PMID 34201791, 2021). "Here we discover Indoleamine-2,3-dioxygenase-1 (IDO1)+ Paneth cells in the stem cell niche of intestinal crypts and tumors, which promoted immune escape of colorectal cancer (CRC)." (PMID 32444775, 2020). "The consensus molecular subtype I (CSM I) for colorectal carcinoma is characterized by a high expression of PD-1, CTLA-4, IDO1 and other immune checkpoints." (PMID 31960110, 2020). "In colorectal cancer (CRC), IDO-1 overexpression correlates with reduced tumor infiltration by lymphocytes, increased rates of hepatic metastases, and a poor clinical outcome." (PMID 25881064, 2015). "For this purpose, we checked whether the expression of IDO1 protein in DLD-1 and HT-29 colorectal cancer lines decreased under the impact of the tested compound combination." (PMID 38201550, 2023). "In our study, it implied that IDO1 and COX2 could be a feasible marker for prognosis for colorectal cancer patient with liver oligometastases who seemed could benefit from surgery for both primary site and liver metastatic site." (PMID 36983678, 2023). "It is unclear whether IDO1 and COX2 expression levels in colorectal cancer (CRC) patients with liver oligometastases could be independent predictors of overall survival (OS) and progression-free survival (PFS)." (PMID 36983678, 2023). "To experimentally test the hypothesis that disruption of IDO1 impacts both tryptophan and kynurenine pool sizes, we used CRISPR–Cas9-mediated knockout with single-guide RNAs (sgRNAs) targeted against IDO1 human colorectal carcinoma HCT116 cells." (PMID 37337120, 2023). "Although the antitumor efficacy of immune checkpoint blockade (ICB) has been proved in colorectal cancer (CRC), the results are unsatisfactory, presumably owing to the presence of tryptophan metabolism enzymes indoleamine 2,3-dioxygenase 1 (IDO1) and tryptophan 2,3-dioxygenase 2 (TDO2)." (PMID 35571116, 2022). "IDO1+ PCs may lead to the excessive consumption of tryptophan and greater KYN production in colorectal cancer crypts, thereby inhibiting the cell cycle of CD8+ T cells and the expansion of immunosuppressive Tregs." (PMID 36555220, 2022). "Comprehensive immunohistochemical studies have demonstrated significant IDO1 overexpression across diverse malignancies, with particularly high expression observed in triple-negative breast cancer (TNBC), glioblastoma multiforme (GBM), and microsatellite-stable colorectal carcinomas (CRC)." (PMID 40894232, 2025). "However, these trials have not selected patients based on IDO1 tumour positivity, and none of these trials have occurred in patients with colorectal cancer, particularly following inflammation." (PMID 39242821, 2024). "However, there have been no clinical trials investigating the combination of an IDO1 inhibitor and radiation in colorectal cancer." (PMID 36653774, 2023).
colorectal cancer (continued). "However, whether IDO1/COX2 coexpression is correlated with OS and PFS in patients with liver metastases of colorectal cancer remains unknown." (PMID 36983678, 2023). "We observed that CEA level (ng/mL) (>5 vs. ≤5) (p = 0.050; HR = 2.137; 95% CI: 1.001–4.566) and IDO-1/COX2 (Group IV vs. Group I/II/III) (p = 0.002; HR = 2.315; 95% CI: 1.052–5.102) were significantly correlated with OS for patients with liver oligometastases of colorectal cancer." (PMID 36983678, 2023). "We demonstrated that CEA level (ng/mL) (>5 vs. ≤5) (p = 0.007; HR = 2.538; 95% CI: 1.291–5.000) and IDO-1/COX2 (Group IV vs. Group I/II/III) (p = 0.013; HR = 2.347; 95% CI: 1.197–4.608) were significantly correlated with PFS in patients with liver oligometastases of colorectal cancer." (PMID 36983678, 2023). "However, clinical studies do not demostrate IDO1 and COX2 coexpression in CRC patients with liver oligometastases of colorectal cancer." (PMID 36983678, 2023).